DDX60L (DExD/H-box 60 like)
Synonyms: FLJ31033
Tractability: Antibody: the Human Protein Atlas places it where antibodies can reach. PROTAC: ubiquitination databases record sites on it; its protein half-life has been measured.
Gene: Protein-coding gene on chromosome 4 (168,356,735 to 168,537,786, reverse strand). Ensembl gene ENSG00000181381.
Subcellular location (Human Protein Atlas): Cytosol; Plasma membrane
Gene Ontology:
Molecular function: double-stranded RNA binding; single-stranded RNA binding; ATP binding; ATP hydrolysis activity; nucleic acid binding; RNA helicase activity
Biological process: defense response to virus
Cellular component: cytoplasm
Genetic constraint (gnomAD): Loss-of-function variants: 118 observed, 132.55 expected, observed/expected ratio (o/e) 0.89, 90% interval 0.77 to 1.04. The upper end of that interval is the gene's LOEUF score, 1.04, which puts it in group 4 of 6, group 1 being the genes least tolerant of losing a copy. Missense variants: 1,479 observed, 1,476.6 expected, observed/expected ratio (o/e) 1, 90% interval 0.96 to 1.05. Synonymous variants: 527 observed, 538.45 expected, observed/expected ratio (o/e) 0.98, 90% interval 0.91 to 1.05.
Homologues: Orthologues: chimpanzee DDX60L (98% identical), macaque DDX60L (92% identical), Caenorhabditis elegans snrp-200 (10% identical). Paralogues in human: DDX60 (66% identical), SNRNP200 (11% identical), ASCC3 (10% identical), SKIC2 (10% identical), HELQ (10% identical), POLQ (10% identical), HFM1 (10% identical), MTREX (9% identical).
Diseases named in the same sentence as DDX60L in open-access papers:
DDX60L is named in the same sentence as 9 diseases in open-access papers, as found by Europe PMC text mining. Sharing a sentence is not in itself a finding about the gene and the disease. The quoted sentences say what the papers report.
pancreatic ductal adenocarcinoma (3 papers, 2021 to 2022). An infiltrating adenocarcinoma that arises from the epithelial cells of the pancreas. "DExD/H-Box 60 (DDX60L), a member of the DExD/H-Box family of helicases involved in RNA metabolism, has been identified as influencing the survival and metastasis of pancreatic ductal adenocarcinoma (PDAC) cells." (PMID 35892886, 2022). "Dead box polypeptide 60-like (DDX60L) is a member of the DDX family, and it was found that DDX60L is highly expressed in pancreatic ductal adenocarcinoma (PDAC) cells and that DDX60L knockdown significantly induced apoptosis and reduced the metastasis of PDAC cells." (PMID 35223465, 2022).
viral infection (2 papers, 2014 to 2020). "In addition, two further helicases among the PoRs, DDX60L and ZNFX1, were recently described to be involved in the human innate immune response against viral infection." (PMID 32545414, 2020).
Cirrhosis (1 paper, 2022). A chronic disorder of the liver in which liver tissue becomes scarred and is partially replaced by regenerative nodules and fibrotic tissue resulting in loss of liver function. "The low DDX60L expression in HCC patients with no-metastasis, age ≥55 years, tumor size <5 cm, Edmondson grade = I–II, microvascular invasion, no cirrhosis, HBV positivity, tumor stage = III–IV, AFP >20 μg/L, and multiple tumor was associated with poorer prognosis (P <0.05)." (PMID 35223465, 2022).
pancreatic cancer (1 paper, 2021). "DDX60L is highly expressed in pancreatic cancer and related to the overall survival of patients with cancer." (PMID 34789165, 2021). "We investigated the expression of these potential oncogenes (MYEOV, KCNN4, FAM83A, S100A16, and DDX60L) in the pancreatic cancer cell lines of the Cancer Cell Line Encyclopedia (CCLE) database." (PMID 34789165, 2021). "Interestingly, the five genes identified in this study (DDX60L, FAM83A, KCNN4, MYEOV, and S100A16) showed some similar characteristics; they were highly expressed and corelated with poor prognosis in pancreatic cancer." (PMID 34789165, 2021). "The results showed that MYEOV, KCNN4, S100A16, and DDX60L are highly expressed in most pancreatic cancer cell lines, but FAM83A is not." (PMID 34789165, 2021).
systemic lupus erythematosus (1 paper, 2023). An autoimmune multi-organ disease typically associated with vasculopathy and autoantibody production. "In Systemic lupus erythematosus patients, 391 disease‐specific chromatin loops are present, encompassing crucial inflammation‐ and immunity‐related genes, including DDX60L and CXCL13." (PMID 37426677, 2023).
ZIKV infection (1 paper, 2022). "Molecules involved in type I IFN signaling are also increased by ZIKV infection, such as STAT1, DDX60L, DDX60, DDX58, STAT2, and IRF7." (PMID 36142200, 2022).
tumor (2 papers, 2021 to 2022). "The expression levels of DDX60L in HCC tissues and in tissues adjacent to the tumor and their correlation with the clinicopathological features of patients were analyzed." (PMID 35223465, 2022).
cancer (1 paper, 2021). A tumor composed of atypical neoplastic, often pleomorphic cells that invade other tissues. "However, the novel oncogene DDX60L we identified did not influence the proliferation of cancer cells, but significantly influenced their invasive ability." (PMID 34789165, 2021).
DDX60L also shares sentences with these, for which no sentence is quoted: pancreatic adenocarcinoma (1 paper).